GPC3 (glypican 3)
Diseases named in the same sentence as GPC3 in open-access papers (continued):
Sharing a sentence is not in itself a finding about the gene and the disease.
tumor (continued). "Research suggests that CAR-T cells, targeting specific tumor-associated antigens such as AFP and GPC3, can be effective in enhancing T cell responses." (PMID 41514551, 2025). "Beyond its mechanistic contributions to tumor biology, GPC3 plays a critical role in the clinical landscape of HCC." (PMID 40722645, 2025). "Multiplex immunohistochemical staining (GPC3, CD4, Foxp3) revealed distinct tumor immune microenvironments between risk groups." (PMID 40533802, 2025). "One study that combined GPC3-targeted CAR macrophage cells with sorafenib showed significant anti-tumor activity, particularly in smaller tumors, although the effectiveness decreased in larger tumor masses." (PMID 40308592, 2025). "Key advancements include the integration of immune checkpoint inhibitors (ICIs) like PD-1/PD-L1 and CTLA-4 inhibitors into clinical practice and the development of bispecific antibodies and ADCs targeting tumor-specific antigens like glypican-3." (PMID 40621467, 2025). "To address these gaps, we performed a retrospective cohort study to assess the prognostic and predictive significance of tumor GPC3 expression in patients with advanced HCC treated with AB combination therapy." (PMID 41463223, 2025). "Subgroup analysis linked strong GPC3 expression to the presence of vascular invasion (OR: 2.43), late TNM stage (OR: 2.26), and high tumor grade (OR: 3.30)." (PMID 40941632, 2025). "To further evaluate the anti-tumor effects of GPC3-CAR-T cells in vivo, we established a cell line-derived xenograft (CDX) model by subcutaneously injecting GFP/Luc+ Huh7 into immunodeficient NCG mice." (PMID 41372119, 2025). "One CAR recognised GPC3-expressing tumour cells and incorporated a Super IL-2 cytokine module designed to stimulate T-cell activation locally." (PMID 40574837, 2025). "Preclinical studies have demonstrated that GPC3-targeted CAR-T cells effectively inhibit tumor growth." (PMID 40051497, 2025). "We found more than one TA was expressed per tumor, and seven TAs (GPC3, IGF2BP3, NOL4, NR6A1, PKB, PRAME, and SPAG17) were detected in multiple tumors." (PMID 40894019, 2025). "CAR-T cell therapy involves engineering a patient’s T-cells to express a receptor that specifically recognises and binds to tumour-specific neoantigens, such as glypican-3 (GPC3) in BTC." (PMID 39851940, 2024). "In efforts to enhance NK cell-mediated tumor responses, a recent study introduced antibody-based therapies known as NK cell engagers (NKCEs), specifically targeting Glypican-3 (GPC3) in HCC." (PMID 39850799, 2024). "In a phase I trial, patients with advanced HCC showed good tolerability towards GC33, and some patients with high GPC3 expression showed signs of tumor reduction." (PMID 38727261, 2024). "engineered bispecific CAR-T cells targeting both fibroblast activation protein (FAP) and GPC3 simultaneously to address tumor diversity in HCC." (PMID 39569202, 2024). "In a humanised NSG mouse xenograft model, GPC3-CAR-T killed tumour cells at twice the rate of conventional CAR-T cells, and this led to tumour regression." (PMID 38675377, 2024). "In vivo experiments using NOD/SCID mice with SK-HEP-1/GPC3 xenografts demonstrated a substantial suppression of tumor growth upon treatment with NK-92/9.28.z cells." (PMID 38694508, 2024). "Another study confirmed that pretreating the tumor with a recombinant adeno-associated virus bearing the CCL19 gene (AAV-CCL19) increased the infiltration of GPC3 CAR T cells into the tumor tissue and significantly extended the survival of mice." (PMID 38473878, 2024). "They found that the expression of GPC3 predicted larger tumor size, more advanced TNM staging, and increased lymph node involvement." (PMID 39598037, 2024). "These engineered CAR-T cells demonstrated targeted and efficient elimination of GPC3-positive tumor cells in vitro, showcasing enhanced antitumor efficacy in comparison to the second-generation CAR-T cells." (PMID 39569202, 2024).
tumor (continued). "In fact, tumor-to-liver ratios of 12 or greater indicate 89Zr-αGPC3H is highly specific for GPC3-expressing tumors." (PMID 38978570, 2024). "In one patient with advanced HCC, treatment using anti-GPC3-7 × 19 CAR-T resulted in the complete disappearance of the tumor 30 days post-intratumor injection." (PMID 38727261, 2024). "RNA sequencing demarcated tumor models from normal liver cells by displaying high levels of the HB markers GPC3, AFP and IGF2, the proliferation marker Ki67, and the Wnt signaling target AXIN2." (PMID 39529166, 2024). "In some tissues, GPC3 acts as a tumor suppressor gene, while in others it functions as a tumor promoter." (PMID 38919533, 2024). "A logic-gated (log) GPC3-synNotch-inducible CD147 CAR was also generated to mitigate potential on-target/off-tumor toxicity." (PMID 38473878, 2024). "Tumor cells were significantly enriched on the right side of the sample, consistent with the location of the high expression of the marker gene GPC3, in line with the original study’s description of the “tumor zone”." (PMID 38672453, 2024). "ADIRF, tumor-associated genes CLU, FAM13C, as well as NGF, PRELP, RERG, PTGIS, GPC3 genes were among the top 20 overexpressed genes in EcE stromal cell population." (PMID 39169201, 2024). "Further validation was performed in orthotopic xenograft models with endogenous GPC3 expression, showing reduced tumor development." (PMID 38694508, 2024). "Studies have shown that GPC3‐targeted CAR‐T cells can induce sustained tumor regression in mice with HCC." (PMID 38318160, 2024). "Significantly, in a phase I clinical trial, these modified CAR-T cells effectively eradicated the tumor upon intra-tumor administration in a patient with advanced GPC3-positive HCC." (PMID 39569202, 2024). "Here, we report that 89Zr-αGPC3H targets GPC3 comparably to 89Zr-αGPC3M, resulting in highly specific tumor uptake and successful HCC detection." (PMID 38978570, 2024). "Remarkably, in a phase I clinical trial (NCT03198546), these modified CAR T cells completely eradicated the tumor 30 days after intra-tumor injection in a patient with advanced GPC3+ HCC." (PMID 38473878, 2024). "Engineered to latch onto liver cancer cell-specific markers, such as GPC3 and EpCAM, AFNs usher in tumor-focused therapy, sparing healthy cells and elevating treatment safety and efficacy." (PMID 38735927, 2024). "More importantly, the study achieved therapeutic effects of orthotopic HCC tumor model by injecting mouse-derived engineered anti-glypican 3 (GPC3)-CAR-NK cells." (PMID 39310113, 2024). "ERY974 is a bispecific antibody that engages CD3 on T cells and GPC3 on tumor cells that underwent a phase I trial in patients with any GPC3-positive solid tumor type." (PMID 38279258, 2024). "To validate ICG+ cells as liver tumor cells, we chose a second marker of HB and HCC tumor cells, Glypican-3 (GPC3)." (PMID 38727682, 2024). "Other studies have found that in a patient with late-stage HCC, anti-GPC3 IL-7/CCL19 CAR-T therapy resulted in complete tumor disappearance 30 days post-intra-tumor injection." (PMID 37081982, 2023). "In this study, EpCAM/vimentin/GPC3 antibody-modified LMS were used to capture tumor cells with epithelial phenotype, mesenchymal phenotype and GPC3 phenotype." (PMID 36681851, 2023). "Compared with NK cells modified with a random aptamer mutation and unmodified NK cells, G-NK cells induced significant apoptosis/necrosis of GPC3+ tumor cells and secreted cytokines to preserve the intense cytotoxic activities." (PMID 37665421, 2023). "Our result showed that the AUC values of the ROC curves using DDK-1, AXAN2 and GPC3 to distinguish tumor tissue from normal tissue were 0.749, 0.895 and 0.919, respectively." (PMID 37821948, 2023). "It was demonstrated that anti-GPC3-CAR T cells effectively eliminate tumours in patient-derived xenograft murine models of HCC." (PMID 37509293, 2023).
tumor (continued). "In this study, approximately similar specific T cell activation and tumor inhibitory effects were observed among mice immunized with PEG10 and GPC3 epitope or long peptide, placental gp96, and tumor lysate." (PMID 37932427, 2023). "What is more, GPC-3-targeted CAR-NK cells/Vδ1 T cells also exhibit robust anti-tumor activity in HCC." (PMID 36773210, 2023). "To explore the targeted delivery ability of hGC33 scFv‐melittin MVs to GPC3‐positive tumor cells in vivo, we monitored the biodistribution of nP18 at 12, 24, and 36 h postintravenous injection by fluorescence imaging." (PMID 38023709, 2023). "GPC-3, a carcinoembryonic proteoglycan on the tumor cell membrane, and CD133, an endothelial progenitor cell marker, are two popular immunotherapy targets in recent HCC research." (PMID 36773210, 2023). "Because hGC33 scFv MVs loaded with DOX target GPC3‐positive tumor cells specifically, thus reducing the dose of this small molecule drug." (PMID 38023709, 2023). "GPC3 is physiologically expressed in various fetal tissues (liver, lung, kidney, and placenta), but its expression is limited in postnatal non‐tumor tissues due to DNA methylation induced epigenetic silencing." (PMID 37986544, 2023). "In a pre-clinical study, GPC3-CAR and IL-15 showed enhanced anti-tumor activity in mouse xenograft models of GPC3+ solid tumors compared to GPC3-CAR alone." (PMID 37371075, 2023). "We demonstrated that the chaperone gp96 can capture antigenic peptides as an efficient approach for defining tumor rejection oncoantigens in the placenta and provide a basis for developing GPC3 and PEG10 peptide-based vaccines against HCC." (PMID 37932427, 2023). "Dual-targeted CAR-T cells co-expressing GPC3 and asialoglycoprotein receptor 1 (ASGR1) exhibited cytotoxicity against GPC3+ASGR1− and GPC3+ASGR1+ HCC cells in vitro and caused a significant reduction of GPC3+ASGR1+ HCC tumor xenografts in vivo." (PMID 37420216, 2023). "Recent studies have explored novel serum/plasma biomarkers, such as circulating nucleic acids (CNAs), circulating tumor DNA (ctDNA), Glypican-3 (GPC3), and SALL4." (PMID 38173713, 2023). "Therefore, the near-zero expression of GPC3 in normal tissues, low expression in LUAD, and high expression in LUSC led us to hypothesize that GPC3 plays a role in immunotherapy as a tumor-associated antigen of LUSC and becomes a reasonable immunotherapeutic target for LUSC." (PMID 37965271, 2023). "Several tumor associated antigens (TAAs) expressed in liver tumor cells have been exploited for CAR-T cell therapy, including GPC-3, AFP, and CEA." (PMID 37665421, 2023). "We further established an MS-based immunopeptidomic approach for identifying tumor-specific antigens from the placenta and identified GPC3 and PEG10 as HCC antigens with high immunogenicity recognized by T cells." (PMID 37932427, 2023). "In another ongoing phase I clinical trial (NCT03198546), complete tumor disappearance was observed in patients with GPC3+ advanced HCC after 30 days of treatment with intratumor injections of 19.9 × 108 CAR-GPC3 T cells." (PMID 37275909, 2023). "Targeting GPC3 sensitize the PD-1 blockage therapy in GC and significantly increased the tumour infiltrated CD8+ IFN-γ+ T cells." (PMID 37036308, 2023). "For instance, GPC-3, besides being a diagnostic biomarker for HCC, also plays a crucial role in the tumor immune microenvironment." (PMID 37835371, 2023). "GPC-3 is one of the subtypes and regulates tumor formation, differentiation, and metastasis and the immune microenvironment by participating in multiple signaling pathways." (PMID 36824129, 2023).
tumor (continued). "Studies have shown that GPC3 expression levels in HCC tissues are associated with tumor aggressiveness and poor prognosis, including tumor size, vascular invasion, and metastasis." (PMID 38173713, 2023). "89Zr-aGPC3 is highly avid for GPC3, and demonstrated high avidity for the tumor in vivo with minimal surrounding uptake in the normal liver, affording spatially resolute images for easy identification of small tumors." (PMID 37103671, 2023). "Glypian-3 (GPC-3) has been demonstrated to relate with immunoreactivity towards tumor cells and is highly expressed in HCC, becoming a notable candidate target in HCC." (PMID 36936932, 2023). "The GPC3 peptide is considered an ideal vaccine for HCC treatment due to its overexpression on HCC tumor cells and low level on normal cells." (PMID 37275909, 2023). "On the other hand, TCR-engineered T cells specific to glypican-3 (GPC-3) or AFP proved to inhibit tumor progression." (PMID 36765612, 2023). "This soluble form of GPC3 itself has anti-tumor activity as it can block the activation of Wnt signaling induced by GPC3 and therefore inhibit HCC cell proliferation." (PMID 37048069, 2023). "Immuno-PET is being developed for HCC against several tumor-associated antigens including CD146, CD38 and glypican-3 (GPC3)." (PMID 37103671, 2023). "We observed overall reduction in expression of Cyp2e1 in tumor tissues in comparison with normal livers but marked induction of Igf2, Afp, Dlk1, Epcam and Gpc3 in tumor areas." (PMID 37414763, 2023). "Glypican-3 (GPC3) belongs to the glypican family of heparan sulfate proteoglycans and is involved in cell proliferation, survival, and tumor suppression." (PMID 37892997, 2023). "A complete tumor disappearance was observed 30 days after an intratumor injection of anti-GPC3-7 × 19 CAR-T treatment in a patient with advanced HCC enrolled in an ongoing phase 1 clinical trial (NCT03198546)." (PMID 36980692, 2023). "Recently, it has been found that Human-VH-CAR T cells targeting GPC3 lead to tumour eradication in in vitro and in vivo models." (PMID 37509293, 2023). "The HCC blood supply mostly arises from the systemic circulation, and GPC-3 can significantly promote HCC tumor angiogenesis." (PMID 36824129, 2023). "Activation of the oncogenic IGF-1R pathway by GPC3 leads to the initiation and maintenance of the tumor through inhibition of apoptosis and G1 cell cycle development." (PMID 37305177, 2023). "Similar to HepG2 tumor lysates, these two GPC3 and PEG10 precursor peptides complexed with recombinant gp96 exhibited specific cytotoxicity for HepG2 cells but not for SK-Hep-1 cells." (PMID 37932427, 2023). "Clinical trials of HCC have shown that GPC3-CAR-T cells inhibit tumor growth (NCT03198546, NCT02395250, and NCT03146234)." (PMID 37719852, 2023). "The correlation between MVI occurrence and primary disease, age, gender, tumor size, tumor stage, and immunohistochemical characteristics of 13 proteins, including GPC3, CK19 and vimentin, were statistically analyzed." (PMID 36973651, 2023). "In our study, we found GPC3 is mainly up-regulated in CAFs in GC tissue, especially for the deep layer of GC, which means GPC3high CAFs is correlated with the tumour progression of GC." (PMID 37036308, 2023). "The activity of CYT-303 is higher compared to the monospecific GPC3 or NKp46 mAbs, suggesting that co-engagement of NKp46 and GPC3, forming an immunological synapse, is desired for optimal NK cell functions against tumor cells." (PMID 37048069, 2023). "Due to overexpression of transferrin receptor in GPC3-positive HCC patients, the iron content of the tumor increases, making the R2* map potentially an excellent way for evaluating GPC3 status in HCC." (PMID 38023195, 2023). "A Phase I clinical trial of the anti-GPC3 monoclonal antibody Codrituzumab combined with atezozumab showed that the agents were well-tolerated and effective in reducing tumor growth in patients with advanced HCC." (PMID 35251989, 2022).
tumor (continued). "Analysis of antigen-specific de novo T cell responses revealed significantly elevated numbers of CD8+ T cells specific for GPC3 epitope in tumor-infiltrating lymphocytes from DEXP&A&N-treated mice than mice treated with DEXAFP and PBS." (PMID 35488312, 2022). "Very few colocalization of Gal-9 and GPC3 was observed in all the specimens we examined, indicating that most tumor cells didn’t have Gal-9 expression." (PMID 35202002, 2022). "Among the HCC marker genes, a higher percentage of tumours showed GPC3 expression compared to AFP expression [73% (23/30) vs. 43% (13/30)]." (PMID 36345011, 2022). "Both conditions resulted in an increase of isolated cells and tumor masses outside SA territories, suggesting that rUnc5DlglgTSP has GPC3-independent functions in this system." (PMID 36240740, 2022). "The study further showed that the tumor-suppressive effect of miR-4510 was mediated through direct targeting of GPC3 mRNA and inactivation of Wnt/β-catenin transcriptional activity and signaling pathways." (PMID 35050429, 2022). "CAR-T cells are cells that can specifically recognize different tumor-surface antigens, in this case glypican-3." (PMID 35683190, 2022). "Our in vitro results indicated that CoG133-CAR T cells were activated by GPC3+CD133+ tumor cells and exhibited vigorous antitumor activity against double-positive cell lines." (PMID 35879685, 2022). "Glypican-3 (GPC3) is an oncofetal tumor antigen that is an attractive target for chimeric antigen receptor T cell therapy due to its highly restricted expression on normal tissue and high prevalence in several solid tumors." (PMID 35937502, 2022). "BOXR1030 expansion in GPC3+ tumor tissues was observed, demonstrating the target-specificity of BOXR1030." (PMID 35507536, 2022). "The aim of the present study was to complete validation of a GPC3 antibody for use in immunohistochemistry (IHC), investigate the expression of GPC3 in MCC by IHC and to assess its association with tumor characteristics, MCPyV status, and patient outcome." (PMID 35937502, 2022). "The killing ability of CD8+ lymphocytes in the Ad-IL12/GPC3 group against tumor target cells was significantly higher than that of other groups." (PMID 36139670, 2022). "While there were cases with CAF-SULF2, glypican-3 and tumour nuclear β-catenin, as well as cases reminiscent of in vitro data − with membranous accumulation of β-catenin − there were no consistent, significant associations with CAF-SULF2 (data not shown)." (PMID 36589727, 2022). "In this study, to stimulate a strong immune response and functional anti-tumor effects, adenovirus vaccine vector expressing GPC3 were generated for a prime-boost regimen." (PMID 36139670, 2022). "The results show that the Ad-IL-12/GPC3 vaccine displayed a more substantial anti-HCC effect by reprogramming the tumor microenvironment and enhancing the response of induced multifunctional CD8+ T cells." (PMID 36139670, 2022). "The result of immunohistochemical staining showed that the number of tumor-infiltrating CD8+ T cells in the Ad-IL-12/GPC3 group was significantly higher than that in other groups." (PMID 36139670, 2022). "SULF2 derived from CAFs modulates glypican-3/β-catenin signalling but also the HCC immune TME, associated with tumour progression and therapy resistance via activation of the TAK1/IKKβ/NF-κB pathway." (PMID 36589727, 2022). "Whereas Alb-R26Met tumours are Afp, Spp1, Gpc3, and Epcam positive, as we previously documented, Myc-R26Met tumours do not express these markers (or at lower levels)." (PMID 36433941, 2022). "Excitingly, glypican-3 (GPC-3) can act as an anchoring carcinoembryonic proteoglycan on tumor cell membranes in combination with CAR-T technology to provide a new light for immunotherapy of solid tumors, especially HCC." (PMID 36307751, 2022).